PTH (parathyroid hormone)
Diseases named in the same sentence as PTH in open-access papers (continued):
Sharing a sentence is not in itself a finding about the gene and the disease.
Hypocalcemia (continued). "So far, there is no consensus or guideline on when to initiate postsurgical hypocalcemia with active vitamin D analogs and calcium supplements, or PTH substitution." (PMID 34863037, 2021). "Preoperative magnesium, preoperative PTH and Hashimoto's thyroiditis were not significant predictors of transient hypocalcemia." (PMID 33718114, 2021). "In particular, poor vascular perfusion on ICGA did not correlate with a postoperative reduction in PTH levels or transient hypocalcemia." (PMID 34359693, 2021). "Hence, ADH is characterised by hypocalcaemia, varying from mild asymptomatic to severe in about half of ADH patients and improper low or normal PTH levels." (PMID 34068220, 2021). "Similarly, PTH levels start to increase at normal or near normal GFR levels, long before the onset of hypocalcemia or hyperphosphatemia." (PMID 34371838, 2021). "Furthermore, parathyroid hormone (PTH) and calcium levels must be drawn for total or completion thyroid surgery in the post-anesthetic care unit to assess for potential hypocalcemia prior to discharge." (PMID 34394008, 2021). "Within the department, it was noted that PTH levels were often not available within the appropriate timeframe and there were challenges in identifying and treating patients who developed hypocalcaemia." (PMID 34164240, 2021). "Preoperative serum concentrations of 25(OH) vitamin D were not predictors for post-total thyroidectomy hypocalcemia, whereas postoperative parathyroid hormone influenced the occurrence of this complication." (PMID 31492617, 2021). "Biochemical studies show hypocalcemia, hypophosphatemia, and elevated ALP and PTH serum levels." (PMID 34199067, 2021). "The subnormal 25-OH-vitamin D levels were not always related to hypocalcemia or a rise in PTH levels." (PMID 34113519, 2021). "Female sex, age < 55 years and PTH levels < 12 pg/mL were predictive of postoperative temporary hypocalcemia, while the incidental parathyroidectomy did not increase the risk of hypocalcemia." (PMID 34575224, 2021). "A PTH level paired with serum calcium and phosphate, and urine renal tubular resorption of phosphate (TRP) measurement will help differentiate between hypophosphatemia or hypocalcaemia." (PMID 33614549, 2021). "We found that the mean pre-RAI PTH and serum calcium levels in the hypocalcemia group at five days post-RAI were lower than those in the normal serum calcium group." (PMID 34122347, 2021). "Plasma PTH levels increased in the absence of a significant reduction of serum albumin-corrected calcium levels, and none of the patients experienced hypocalcemia or fragility clinical fractures." (PMID 33204260, 2020). "Parathyroid hormone (PTH) and calcium levels are often measured after thyroid surgery, as hypocalcemia, secondary to postoperative hypoparathyroidism, is one of the most frequent (ranging between 7% to 37%) complications in patients undergoing bilateral thyroid resection." (PMID 33260912, 2020). "The mean PTH level was significantly lower in patients who developed hypocalcemia than in patients who did not." (PMID 32774362, 2020). "Although conventional therapy increases intestinal calcium absorption and corrects hypocalcemia, it does not replace other functions of PTH and, in the absence of PTH’s calcium-retaining effect in the kidney, can lead to hypercalciuria." (PMID 32765831, 2020). "In reduced eGFR only (<90 mL/min × 1.73 m2), low urine Ca/Cr independently related to low serum 1,25-dihydroxyvitamin D (p = 0.002) and did not relate to hyperphosphatemia, high serum parathyroid hormone, or hypocalcemia (p ≥ 0.14)." (PMID 33371520, 2020). "Besides having greater mean baseline PTH values, elderly women showed a greater sensitivity of response of PTH levels to intravenous EDTA‐induced hypocalcemia." (PMID 32803112, 2020). "This suggests that discontinuation was largely dependent on PTH rather than hypocalcemia (Online Resource 8)." (PMID 31848883, 2020).
Hypocalcemia (continued). "A diagnosis of pseudohypoparathyroidism without phenotypic defects, was made due to hypocalcaemia and increased parathyroid hormone levels with cerebral calcifications." (PMID 31856822, 2019). "A connection between types of PHP and the time point for development of PTH resistance and hypocalcemia has not been established." (PMID 31892351, 2019). "Conventional therapy of hypoparathyroidism consists of the use of calcium supplements, and active vitamin D. This therapeutic approach addresses the hypocalcemia of hypoparathyroidism, but fails to provide a physiologic replacement for the lack of PTH." (PMID 30540559, 2019). "In patients with or without symptomatic hypocalcaemia, a significant difference was observed in calcium and PTH levels between pre- and post-operative levels." (PMID 30989072, 2019). "The PTH resistance is often absent at birth so the resistance to PTH and hypocalcemia often develops over time." (PMID 31892351, 2019). "The abrupt reduction in serum PTH after PTX may provoke a series of electrolyte abnormalities, such as hypocalcaemia, hypomagnesaemia, hypophosphataemia, and hyperkalaemia." (PMID 31221111, 2019). "If the PTH is in the normal reference range and is not elevated in the presence of hypocalcemia, this would also be indicative of impaired parathyroid response to the hypocalcemic insult and diagnostic of hypoparathyroidism." (PMID 30540559, 2019). "Most of the CCC group patients achieved KDOQI targets (serum PTH 150–300 pg/mL, Ca 8.4–9.5 mg/dL, P 3.5–5.5 mg/dL, CaxP product < 55 mg2/dL2) and none had hypocalcemia." (PMID 29439405, 2018). "Resistance to PTH is also present in patients with mutations in PRKAR1A5,6,15,20,63,64; however, hypocalcaemia has not been documented in these patients yet." (PMID 29959430, 2018). "In spite of these high FGF23 levels, rFGF23 had no suppressive effect on PTH levels during hypocalcemia." (PMID 29063159, 2018). "Hypoparathyroidism is a rare endocrine disorder characterized by hypocalcemia and hyperphosphatemia due to low or absent circulating levels of parathyroid hormone (PTH)." (PMID 29099947, 2018). "Symptomatic hypoparathyroidism [symptomatic hypocalcemia without elevated serum parathyroid hormone (PTH)] in patients with thalassemia is relatively rare." (PMID 29726397, 2018). "Decreased 1,25-dihydroxyvitamin D levels results in chronic parathyroid gland stimulation due to lack of inhibitory effects of 1,25-dihydroxyvitamin D on PTH gene transcription and lack of inhibitory feedback to the parathyroid gland by subtle hypocalcemia." (PMID 30200452, 2018). "VDD was not a significant risk factor for hypocalcemia following TT+CCND, and did not affect the accuracy of postoperative PTH as a predictor of postoperative hypocalcemia." (PMID 29100453, 2017). "PTH resistance: PTH resistance is defined as elevated PTH with or without hypocalcemia, hyperphosphatemia." (PMID 29280743, 2017). "Trung and colleagues concluded a postoperative PTH level <12 pg/ml drawn after 1 hour accurately correlated with the development of significant hypocalcemia, with a positive predictive value of 90% and a negative predictive value of 98%." (PMID 28955671, 2017). "In conclusion, although VDD was common in our cohort, it was not a significant risk factor for hypocalcemia following TT+CCND, and did not affect the accuracy of postoperative PTH as a predictor of post-thyroidectomy hypocalcemia." (PMID 29100453, 2017). "Another study also revealed that postoperative serum PTH was not a reliable predictor for hypocalcemia in patients with VDD based on a series of 203 cases." (PMID 29100453, 2017). "There was also a significant difference in the percentage of postoperative PTH less than 1.6 pmol/L in patients with or without symptomatic hypocalcemia in both the groups (P = 0.000 and 0.001, respectively)." (PMID 29100453, 2017).
Hypocalcemia (continued). "In contrast, other authors reported that postoperative serum PTH had lower accuracy in predicting hypocalcemia in patients with VDD when compared to patients without VDD." (PMID 29100453, 2017). "Lack of functional PTH results in hypoparathyroidism, which is a rare disease characterized by hypocalcemia." (PMID 27857062, 2016). "Immediate post-operative parathyroid hormone (PTH) was within normal range (1.6–6.9 pmol/L) with no symptomatic hypocalcaemia." (PMID 26873163, 2016). "Pseudohypoparathyroidism type 1b (PHP1b) is characterized by hypocalcemia, hyperphosphatemia, increased levels of circulating parathyroid hormone (PTH), and no skeletal or developmental abnormalities." (PMID 27415614, 2016). "Patients present with hypocalcemia, hyperphosphatemia, low magnesium levels, and low or low-normal levels of PTH." (PMID 27803672, 2016). "When the production of PTH is reduced or absent, low PTH is inadequate to maintain normocalcemia and normophosphatemia, thus the biochemical findings of the disease, such as hypocalcemia, hyperphosphatemia, and low PTH ensue." (PMID 28138323, 2016). "They concluded that intact PTH alone did not accurately predict clinically relevant postoperative hypocalcemia and that the optimal cut-offs of intact PTH considering serum calcium levels should be needed." (PMID 25691901, 2015). "As previously reported, serum albumin-corrected calcium decreased though none of the patients experienced hypocalcemia, while plasma PTH levels tended to increase." (PMID 25873952, 2015). "The renal synthesis of 1,25-(OH)2D from its precursor, 25(OH)D is a rate-limiting step and is tightly regulated by serum-(OH)2D, parathyroid hormone (PTH), FGF23, calcium, and phosphate, with renal 1α-hydroxylase being stimulated by PTH, hypophosphatemia, or hypocalcaemia, and inhibited by FGF23." (PMID 26132292, 2015). "There were no cases of postoperative hypocalcemia in either groups, in fact, the values of serum calcium and parathyroid hormone, which are considered predictors of hypocalcemia, were within standard values." (PMID 25392807, 2014). "Primary hypoparathyroidism, one of the most serious complications following thyroid surgery, is characterized by hypocalcemia and hyperphosphatemia with absent or inappropriately low levels of PTH." (PMID 25348653, 2014). "Low 25-OHD was not a significant factor for hypocalcemia and did not lower the accuracy of quick PTH in predicting postthyroidectomy hypocalcemia." (PMID 22968355, 2013). "The PTH level in the youngest infant in this series was not elevated in response to hypocalcaemia (PTH 16 ng/L)." (PMID 23599910, 2013). "Preoperative 25-OHD level was also not a significant factor for hypocalcemia in patients with PTH-SC <1.5 pmol/L." (PMID 22968355, 2013). "Nevertheless, if oral calcium and calcitriol requirements were analyzed more closely, none of the three patients with PTH-SC >1 pmol/L required both oral calcium and calcitriol on discharge, suggesting that they suffered from only mild hypocalcemia." (PMID 22399155, 2012). "Therefore, perhaps in the future, patients with PTH-SC >1 pmol/L could be discharged on the same day of surgery and be instructed to take oral calcium when hypocalcemic symptoms develop as the chance of a life-threatening episode of severe hypocalcemia would seem unlikely in this group of patients." (PMID 22399155, 2012). "The same was seen by Lam & Kerr34 in a study enrolling 40 patients, in which no cases of hypocalcemia were observed in subjects with normal postoperative i-PTH levels." (PMID 23108824, 2012). "The diagnosis is simply based on blood calcium, phosphorus, and parathormone (PTH) levels: hypocalcemia, hyperphosphatemia, inadapted normal/low PTH without any kidney failure." (PMID 22876245, 2012). "In this original study, which is based on the classical teaching of rickets staging, hypocalcemia was attributed to lack of PTH secretion in the first stage of VDDR." (PMID 21274319, 2010).
Hypocalcemia (continued). "Indeed, mice expressing high systemic levels of FGF-23 (R176Q) exhibit hypocalcemia and subsequent development of secondary HPT, even though their elevated PTH levels are likely to aggravate the prevailing hypophosphatemia." (PMID 21234310, 2010). "In practical terms, leveraging both conventional metrics (e.g., extreme PTH/ALP elevations, hypocalcemia) and newer markers (e.g., P1NP, TRAP-5b) within an interpretive scoring system may further facilitate clinicians to pinpoint truly high-risk patients before they develop severe hypocalcemia." (PMID 41227247, 2025). "Additionally, HIV itself may impair PTH secretion, while TDF can favour hypocalcaemia, potentially resulting in both hypoparathyroidism and secondary hyperparathyroidism." (PMID 41295288, 2025). "Hypocalcemia is frequently observed in ICU patients and may result from diverse mechanisms, including decreased parathyroid hormone secretion, intracellular sequestration of calcium, redistribution into third spaces such as ascitic fluid, and hypomagnesemia, especially in septic states." (PMID 41002995, 2025). "However, in multivariate logistic regression, pre‐operative PTH was not identified as an independent predictor of postoperative hypocalcemia (95% CI: 0.999–1.001)." (PMID 40517023, 2025). "However, it is best defined as an undetectable or inappropriately low postoperative PTH combined with hypocalcemia, with or without hypocalcemic symptoms." (PMID 40177730, 2025). "However, it did not prevent a postoperative decrease in intact parathyroid hormone levels nor did it lower the incidence of hypocalcemia or HPT after TT." (PMID 40786097, 2025). "The third-generation assay can have good results in patients with primary and secondary hyperparathyroidism, but may not be superior to intact PTH for diagnosis of HPT and other conditions associated with hypocalcemia." (PMID 40786097, 2025). "Elevated intact parathyroid hormone level and hypocalcemia with no other metabolic abnormalities." (PMID 40129423, 2025). "Although our study did not measure PTH levels, the relationship between the extent of surgery and postoperative hypocalcemia is similar, suggesting that surgical techniques that preserve parathyroid function may reduce the risk of prolonged hypocalcemia." (PMID 39640157, 2024). "In the present cohort, there were 11 patients who met the criteria for the definition of permanent hypoparathyroidism (hypocalcemia with inadequately low PTH over 6 months after surgery), but did not suffer from symptoms of hypocalcemia and were not prescribed with calcium or vitamin D supplements." (PMID 39636417, 2024). "This difference may also be due to elevated PTHrP during lactation, whereas hypocalcemia increases circulating PTH levels, and it is not clear if hormones target distinct bone sites." (PMID 38661340, 2024). "The mutant mice did not have hypocalcemia nor lower serum PTH." (PMID 38697929, 2024). "This phenomenon may partially explain why patients with progressive CKD seen in this study demonstrated elevated PTH without hypocalcemia." (PMID 39071944, 2024). "Additionally, the timing of PTH measurement also plays a significant role in determining postoperative hypocalcemia, and there is no standardised timing for measuring PTH following NIRAF use." (PMID 38472977, 2024). "While our data does not show a lowering of the frequency of hypocalcemia in response to single daily PTH injections compared to conventional therapy, there was a decrease in the frequency of hypocalcemia in response to multiple daily PTH injections and PTH pump therapy." (PMID 38562130, 2024). "Interestingly, 17 patients (7%) with a postoperative PTH value of <12 pg/mL developed a definitive hypocalcemia, while no patient in the group with postoperative PTH levels > 12 pg/mL developed a definitive hypoparathyroidism." (PMID 36902740, 2023). "Other outcomes concerning serum PTH, serum calcium and hypocalcemia did not change." (PMID 38050273, 2023).
Hypocalcemia (continued). "In multivariate analysis, age < 40 years, postoperative PTH levels < 12 pg/mL, a diagnosis of thyroid cancer, and neck dissection were predictive of postoperative hypocalcemia, while gender and the extent of surgery did not relate to an increased risk of hypocalcemia." (PMID 36902740, 2023). "After thyroidectomy, the monitoring of PTH and serum calcium levels are the best predictors for identifying hypoparathyroidism and treating the consequent symptomatic hypocalcemia; however, there is a clear lack of consensus about the timing, patient selection, and cut-off points for PTH levels." (PMID 36902740, 2023). "After their analysis, the authors suggested that hypoparathyroidism could be defined as the presence of an undetectable or inappropriately low postoperative PTH level in the context of hypocalcemia with or without hypocalcemic symptoms." (PMID 36902740, 2023). "The negative Ca balance and systemic hypocalcemia in citrate CVVH can lead to further activation of parathormone (PTH) which may already have been activated due to renal dysfunction." (PMID 36899104, 2023). "Diagnosis may be difficult in the absence of one or several biochemical features (hypocalcemia or hyperphosphatemia), also considering that PTH resistance is usually absent at birth and develops over time." (PMID 37854194, 2023). "Second, PTH concentration was not routinely measured in all patients with hypocalcemia." (PMID 35663648, 2022). "Our previous study found that significantly elevated PTH could not stimulate the expression of FGF23 in 1α-hydroxylase knockout mice with 1,25(OH)2D3 deficiency and hypocalcemia." (PMID 35801203, 2022). "However, not all authors are in agreement that POD1 PTH levels reliably predict hypocalcaemia, while cut-off PTH levels on POD1 for safe patient discharge are not clearly defined." (PMID 35247092, 2022). "Selberherr reported no cases of symptomatic hypocalcaemia with POD1 PTH levels ≥ 15 pg/ml." (PMID 35247092, 2022). "In practice, we intend to utilise an initial cinacalcet dose of 30 mg/day in most patients, except those with baseline PTH > 30 pmol/L, with a view to reduce drug acquisition costs and possibly reducing the incidence of hypocalcaemia, without diminishing the effect on Ca." (PMID 34647901, 2021). "Hypocalcaemia was observed more frequently in patients taking higher dose cinacalcet (2 out of 8 patients vs 2 out of 78 patients) though patients initiated at a dose of 60 mg/day in our historical cohort were not stratified according to baseline PTH." (PMID 34647901, 2021). "In addition, a past research asserts that hypocalcemia can increase parathyroid hormone (PTH) secretion via a negative feedback loop, which results in oxidative stress." (PMID 34229683, 2021). "In addition, 38 (1.5%) patients were defined as protracted hypoparathyroidism, and 22 (0.9%) patients did not recover from reduced PTH levels and symptomatic hypocalcemia within 12 months." (PMID 34262932, 2021). "Interestingly, hypocalcemia in our patients was independent of vitamin D and PTH levels, and these measures were not significantly different between our cases and controls." (PMID 33936225, 2021). "Interestingly, five patients (8%) with a postoperative PTH value < 12 pg/mL developed a definitive hypocalcemia, while no patient in the group with postoperative PTH levels > 12 pg/mL developed a definitive hypoparathyroidism." (PMID 34575224, 2021). "Some authors suggest that PTH may not be the only determinant for the development of hypocalcemia and that other factors may play a major role such as vitamin D deficiency, dietary habits, and other metabolic disorders such as hypomagnesemia." (PMID 34574074, 2021). "In their opinion, PSHP should be considered as permanent if PTH value does not recover within 1 year after surgery or its level is greater than or equal to 10 pg/ml, but the patient still needs medical correction of hypocalcemia symptoms." (PMID 34513060, 2020).